MIR374B (microRNA 374b)
Synonyms: hsa-mir-374b; MIRN374B; mir-374b
Gene: MicroRNA gene on chromosome X (74,218,547 to 74,218,618, reverse strand). Ensembl gene ENSG00000212027.
Gene Ontology:
Biological process: miRNA-mediated post-transcriptional gene silencing
Homologues: Orthologues: chimpanzee ptr-mir-374b (100% identical), macaque mml-mir-374b (100% identical), pig MIR374B (96% identical), mouse Mir374b (92% identical). Paralogues in human: MIR374A (75% identical).